NT5M (5',3'-nucleotidase, mitochondrial)
Description:
Dephosphorylates preferentially the 5'- and 2'(3')-phosphates of uracil and thymine (deoxy)ribonucleotide monophosphates. Shows low activity toward dGMP and marginal activity toward dIMP.
Synonyms: dNT-2; DNT2; mdN
Tractability: Small molecule: a structure with a bound ligand is known; it has a high-quality binding pocket. PROTAC: its protein half-life has been measured; a small molecule that binds it is known.
Target class: Enzyme; Phosphatase
Gene: Protein-coding gene on chromosome 17 (17,303,331 to 17,347,663, forward strand). Ensembl gene ENSG00000205309.
Subcellular location: Mitochondrion
Pathways (Reactome):
Metabolism: Pyrimidine catabolism
Gene Ontology:
Molecular function: 3'-nucleotidase activity; 5'-nucleotidase activity; nucleotidase activity; 5'-deoxynucleotidase activity
Biological process: dGMP catabolic process; dTMP catabolic process; dUMP catabolic process; GMP catabolic process; TMP catabolic process; UMP catabolic process; DNA replication; pyrimidine deoxyribonucleotide catabolic process; deoxyribonucleotide catabolic process
Cellular component: mitochondrion; mitochondrial matrix
Genetic constraint (gnomAD): Loss-of-function variants: 23 observed, 21.43 expected, observed/expected ratio (o/e) 1.07, 90% interval 0.77 to 1.52. The synonymous counts are far from expectation, so gnomAD's model fits this gene poorly and the ratio says little. Missense variants: 320 observed, 274.83 expected, observed/expected ratio (o/e) 1.16, 90% interval 1.06 to 1.28. Synonymous variants: 167 observed, 109.89 expected, observed/expected ratio (o/e) 1.52, 90% interval 1.34 to 1.73.
Homologues: Orthologues: chimpanzee NT5M (99% identical), pig NT5M (86% identical), rat Nt5m (85% identical), mouse Nt5m (84% identical), guinea pig NT5M (72% identical), tropical clawed frog nt5m (70% identical), dog NT5M (68% identical), macaque NT5M (59% identical). Paralogues in human: NT5C (52% identical).
Diseases named in the same sentence as NT5M in open-access papers:
NT5M is named in the same sentence as 3 diseases in open-access papers, as found by Europe PMC text mining. Sharing a sentence is not in itself a finding about the gene and the disease. The quoted sentences say what the papers report.
HIV-1 infection (1 paper, 2015). The type species of lentivirus and the etiologic agent of acquired immunodeficiency syndrome (AIDS). "Expression of NT5M, a 5’-nucleotidase gene, was shown to vary (downregulation in macrophages) in response to Tenofovir, a pre-exposure prophylaxis used to prevent HIV-1 infection." (PMID 25884674, 2015).
cancer (1 paper, 2022). A tumor composed of atypical neoplastic, often pleomorphic cells that invade other tissues. "GEPIA2 database analysis of 33 cancer types showed the following top 10 ALKBH5-related genes: GID4 (R=0.71), TOP3A (R=0.67), MAPK7 (R=0.66), NT5M (R=0.61), FLII (R=0.59), ZNF18 (R=0.57), DRG2 (R=0.57), COPS3 (R=0.56), MED9 (R=0.56) and PRPSAP2 (R=0.56) (all P<0.0001)." (PMID 35444654, 2022).
NT5M also shares sentences with these, for which no sentence is quoted: tumor (1 paper).